ZBED8 (zinc finger BED-type containing 8)
Synonyms: FAM200C; Buster3; C5orf54
Tractability: PROTAC: ubiquitination databases record sites on it.
Gene: Protein-coding gene on chromosome 5 (160,393,148 to 160,400,091, reverse strand). Ensembl gene ENSG00000221886.
Subcellular location (Human Protein Atlas): Nucleoplasm
Gene Ontology:
Molecular function: protein binding
Cellular component: nucleoplasm
Genetic constraint (gnomAD): Loss-of-function variants: 32 observed, 41.45 expected, observed/expected ratio (o/e) 0.77, 90% interval 0.58 to 1.04. The upper end of that interval is the gene's LOEUF score, 1.04, which puts it in group 4 of 6, group 1 being the genes least tolerant of losing a copy. Missense variants: 677 observed, 737.49 expected, observed/expected ratio (o/e) 0.92, 90% interval 0.86 to 0.98. Synonymous variants: 230 observed, 259.92 expected, observed/expected ratio (o/e) 0.88, 90% interval 0.79 to 0.99.
Homologues: Orthologues: chimpanzee FAM200C (99% identical), macaque FAM200C (99% identical), dog FAM200C (95% identical), rabbit FAM200C (93% identical), pig FAM200C (92% identical), guinea pig FAM200C (91% identical). Paralogues in human: ZBED5 (32% identical), SCAND3 (31% identical), ZBED11 (31% identical), ZBED8L (28% identical), EPM2AIP1 (20% identical), THAP12 (13% identical), ZMYM6 (9% identical), GTF2IRD1 (9% identical), ZMYM2 (9% identical), KIAA1958 (9% identical), ZMYM4 (9% identical), GTF2I (8% identical), and 6 more.